BASP1 (brain abundant membrane attached signal protein 1)
Diseases named in the same sentence as BASP1 in open-access papers (continued):
Sharing a sentence is not in itself a finding about the gene and the disease.
tumor (39 papers, 2015 to 2026). "BASP1 encodes a neuronal signaling protein and transcriptional corepressor, from which tumor-suppressive functions have been described in avian cell systems and in multiple human cancer cell types." (PMID 41785318, 2026). "In this study, differ from the known function of BASP1 as a tumor suppressor, we identified that BASP1 was overexpressed in brain metastases and associated with poor outcomes." (PMID 33042262, 2020). "Recently, BASP1 was found to be aberrantly expressed in different cancers and implicated in regulating cell proliferation, metastasis, apoptosis and angiogenesis and acted as either a tumor suppressor or oncogene." (PMID 36776328, 2023). "In these tumor cells BASP1 suppression is caused by specific miR-191-mediated mRNA degradation." (PMID 31058089, 2019). "Immune infiltration analysis revealed significant associations between the four genes (BASP1, CCL8, FCGR1B, FKBP11) used for risk stratification and tumor microenvironment composition in KIRC." (PMID 40909125, 2025). "Here, GSDMD was attached to the exosome surface by the exosome membrane protein BASP1 to increase the content of GSDMD in tumor cells." (PMID 38762500, 2024). "We demonstrated that BASP1 suppressed immunogenic ferroptosis to induce immunosuppressive tumor microenvironment." (PMID 36776328, 2023). "Upregulated miR-191 expression promotes EMT and activates the Wnt pathway for tumor promotion through the inhibition of BASP1." (PMID 36980828, 2023). "THBS2 (thrombospondin 2), BASP1 (brain acid soluble protein 1), and NPR3 (natriuretic peptide receptor 3) are tumor-suppressor genes, for which downregulation is associated with poor prognosis." (PMID 36980828, 2023). "The mechanism by which BASP1 regulates tumor immunity needs to be further verified in vivo and in vitro." (PMID 37243901, 2023). "Depending on the cellular context, both, oncogenic and tumor suppressor functions of BASP1 have been described." (PMID 38049829, 2023). "In essence, Basp1 is a membrane-bound protein that plays a role in apoptosis, differentiation and transcriptional regulation and is a potential tumour suppressor." (PMID 37226132, 2023). "To further explore the role of BASP1 in tumor immunity, we analyzed the correlation between BASP1 expression levels and those of immune checkpoints and immune cell surface markers in GC." (PMID 37243901, 2023). "Several studies have demonstrated that BASP1 acts as a tumor suppressor, for example in hepatocellular carcinoma, gastric cancer, and breast cancer." (PMID 35982799, 2022). "We conclude that the myristoylation of BASP1 plays a partial role in its tumor suppressor function in K562 cells." (PMID 35982799, 2022). "We find that the N-terminal myristoylation of BASP1 controls its ability to modulate the chromatin environment and is needed for the full tumor suppressor activity of BASP1." (PMID 35982799, 2022). "Consistent with its tumor suppressor activity, BASP1 has a role in maintaining the differentiated state and is required to maintain the functional differentiated state of taste receptor cells in mice." (PMID 35982799, 2022). "We found that BASP1-G2A is partially defective in tumor suppressor function which is consistent with the retention of chromatin modification and transcriptional regulatory function." (PMID 35982799, 2022). "It will be interesting to determine if BASP1 myristoylation plays a similar role in its tumor suppressor activity in other cell types." (PMID 35982799, 2022). "In accordance with this, we find that the tumor suppressor activity of BASP1 is also partially dependent on its myristoylation." (PMID 35982799, 2022).
tumor (continued). "Cox proportional regression model was used to identify a four-gene (WIPF1, PPIB, BASP1, PLOD2) signature that were significantly associated with overall survival (OS), and all the four genes were significantly upregulated in tumor tissues." (PMID 34257533, 2021). "Recently, tumor‐suppressive functions of BASP1 have been observed in several human cancer cell types." (PMID 31944520, 2020). "This corroborates our original finding that BASP1 strongly interferes with v‐Myc‐induced oncogenicity and displays properties of a tumor suppressor." (PMID 31944520, 2020). "Ectopic BASP1 expression inhibits growth of thyroid cancer cell lines and tumor formation in xenografts." (PMID 31944520, 2020). "Strong support for the proposal that BASP1 acts as a potential tumor suppressor came from recent observations in human and animal cancer." (PMID 31944520, 2020). "Based on these discoveries, we proposed that BASP1 displays properties of a putative tumor suppressor." (PMID 31944520, 2020). "The BASP1 gene is downregulated in most mammalian cancers, and tumor‐suppressive functions of BASP1 were observed in several human cancer models." (PMID 31944520, 2020). "The tumor promoters BASP1, GPC1, PSAT1 and SH3BGRL are reported to be typically expressed in macrophages by the Expression Atlas." (PMID 32466393, 2020). "On the other hand, molecules mimicking the tumor suppressive function of BASP1 should represent suitable candidates for drug screening approaches in order to develop novel strategies for specific cancer treatment." (PMID 31058089, 2019). "Nuclear BASP1 participates in gene regulation converting the Wilms tumor transcription factor WT1 from an oncoprotein into a tumor suppressor." (PMID 31058089, 2019). "In distinct human tumors, mainly oncogenic properties are described for GAP43 and MARCKS, whereas for BASP1 a general tumor suppressive function has been reported." (PMID 31058089, 2019). "Whereas GAP43 and MARCKS are oncogenic, tumor suppressive functions have been ascribed to BASP1 and in part to MARCKS depending on the cell type." (PMID 31058089, 2019). "Ectopic BASP1 expression in thyroid cancer cell lines inhibits their growth as well as tumor formation in xenografts." (PMID 31058089, 2019). "To confirm that BASP1 regulates cell proliferation and tumorigenicity, we determine the effect of BASP1 on tumor growth in vivo." (PMID 29089860, 2017). "BASP1 levels correlated significantly with clinical stage (p < 0.001), T classification (larger tumor size, p < 0.001), N classification (lymph node involvement, p < 0.05) and survival or mortality (p < 0.05)." (PMID 29089860, 2017). "In the current study, both SVZ+ and SVZ− GBM tumors showed reduced levels of BASP1, which possibly helps the tumor cells in evading apoptosis." (PMID 28469129, 2017). "Our results so far suggest that BASP1 can function as a transcriptional corepressor for ERα and acts as a tumour suppressor in MCF7 cells." (PMID 28492543, 2017). "Previous studies have reported that BASP1 can act as a tumour suppressor and our data here found that BASP1 can inhibit the tumourigenicity of MCF7 cells." (PMID 28492543, 2017). "Proteome and transcriptome analyses revealed activation of several tumor and metastasis suppressors in BASP1-expressing cells, which also show strong repression of the transformed phenotype in terms of contact inhibition, anchorage-independent growth, and tumor formation." (PMID 41785318, 2026). "We speculated that the high proportion of tumor cells expressing BASP1 or DUSP1 might be one of the reasons for the poor prognosis of advanced GIST." (PMID 38443340, 2024). "Together, our results demonstrated that BASP1 could suppress tumor cell ferroptosis and induce an alteration of immune TME, which might be a predictive biomarker for antitumor immunotherapy." (PMID 36776328, 2023). "BASP1 acts as a tumor suppressor in several cell types and slows the growth of K562 cells." (PMID 35982799, 2022).
tumor (continued). "Several previous studies have demonstrated the tumor suppressor activity of BASP1." (PMID 35982799, 2022). "We concluded that downregulation of the BASP1 gene is a necessary event in MYC‐induced oncogenesis and that the BASP1 protein may act as a potential tumor suppressor." (PMID 31944520, 2020). "In this study, we found that BASP1 expression in GC tissue and cells was significantly lower than that in normal tissue and cells, which was in line with previous studies and suggested that BASP1 might be a tumor suppressor of GC." (PMID 33426068, 2020). "In recent years, studies have shown that abnormal expression and methylation status of the BASP1 gene are closely related to the occurrence and prognosis of certain tumors and that BASP1 may also play a role as a tumor suppressor gene." (PMID 33247706, 2020). "In view of the tumor‐suppressive role of BASP1 which was recently also reported for human cancer, small compounds or peptides based on the BASP1 effector domain could be used in drug development strategies aimed at tumors with high MYC expression." (PMID 31944520, 2020). "BASP1 is identified as a tumor suppressor and is lowly expressed in multiple cancers." (PMID 33426068, 2020). "In view of the tumor‐suppressive potential of BASP1 in human cancer, small compounds or peptides based on the BASP1 ED structure could be developed to expand the spectrum of therapeutic approaches for the treatment of cancers with high MYC expression." (PMID 31944520, 2020). "In several human cell types, BASP1 has a tumor-suppressive function." (PMID 31058089, 2019). "Reactivation of the silenced BASP1 gene may represent an alternative option to interfere with tumor cell viability, because endogenous BASP1 transcription is repressed in multiple human tumor cells." (PMID 31058089, 2019). "The tumor suppressive functions of BASP1 and MARCKS could be exploited to expand the spectrum of future innovative therapeutic approaches to inhibit growth and viability of susceptible human tumors." (PMID 31058089, 2019). "Interestingly, stage I–II (orange) and II–III (red) tumours show a steeper slope than the benign (grey) and grade I (blue) tumours suggesting that the more severe tumours exhibit a lag in BASP1 expression compared with ERα." (PMID 28492543, 2017). "Together, these results suggested that BASP1 promotes tumor growth." (PMID 29089860, 2017). "Indeed, there was a general correlation between the expression of ERα and BASP1 across the samples, whereas the benign tumours were most likely to express the highest level of BASP1." (PMID 28492543, 2017). "Interestingly there is also an inhibitory influence of BASP1 on the oncogene MYC implicating BASP1 as a tumour suppressor." (PMID 26934553, 2016). "In the study of immune checkpoint correlation, we discovered that BASP1 expression was positively linked with a number of immunological checkpoints, such as PD‐1, PD‐L1, and CTLA‐4, which may increase the occurrence of immune escape from tumor cells." (PMID 37243901, 2023). "Silencing BASP1 could substantially induce ferroptotic tumor cells in HNSCC." (PMID 36776328, 2023). "In addition, myristoylation of BASP1 is partially required for its tumor suppressor activity." (PMID 35982799, 2022). "In addition, a growing body of evidence has reported that BASP1 could modulate a variety of tumor cell biological behaviors." (PMID 33426068, 2020). "The analysis revealed significantly higher expression levels of BASP1, FCGR1B, and FKBP11 in KIRC compared to normal adjacent tissues, while CCL8 showed no significant differential expression between tumor and non-tumor tissues." (PMID 40909125, 2025). "Since both BASP1 and REPS2 have been shown to possess tumor-suppressive activities, it will be worthy of further investigation to decipher their potential signaling network with ELAVL2." (PMID 38548861, 2024).
tumor (continued). "In brain metastatic lung cancer, BASP1 reduces the degradation of EGFR protein via the ubiquitin–proteasome pathway and stabilizes EGFR protein, thereby promoting tumor progression." (PMID 37243901, 2023). "BASP1 overexpression strongly interferes with MYC‐induced oncogenesis and the BASP1 protein displays properties of a tumor suppressor, also in human cancer." (PMID 31944520, 2020). "BASP1 is a direct target of miR-191 and BASP1 inhibition by miR-191 leads to transactivation of WT1, which activates the Wnt pathway to promote tumor progression." (PMID 33247706, 2020). "BASP1 is a direct target of miR-191; BASP1 inhibition by miR-191 leads to transactivation of WT1, which activates the Wnt pathway to promote tumor progression." (PMID 29089860, 2017). "Prior studies with the protein BASP1 showed that N-myristoylation and PIP2 recruitment to nuclear speckle domains plays an important function in the transcriptional repression of the Wilm’s Tumor gene (WT1)." (PMID 26470026, 2015). "Besides their functions in neurons, GAP43, MARCKS, and BASP1 are also expressed in non-neuronal cells, and display intrinsic oncogenic or tumor suppressive functions." (PMID 31058089, 2019). "Furthermore, six tumor progression genes (GNAI2, ODC1, APP, TNFRSF12A, BASP1, and LARP6) and nine migration and metastasis‐related genes (MSN, FLOT1, LAMB3, MYL9, ITGB1, FTH1, TPM4, and PMEPA1), which could explain the invasive characteristics of SCC, were identified." (PMID 40776410, 2025).
cancer (29 papers, 2010 to 2026). A tumor composed of atypical neoplastic, often pleomorphic cells that invade other tissues. "GAP43 and BASP1 have previously showed significant associations with tau concentration, together with for example the cancer-associated protein LY6H, and PEBP1 which is believed to have implications for AD." (PMID 33653397, 2021). "BASP1 has been shown to act as an antioncogenic factor in a variety of cancers through its interaction with transcription factors such as WT1 and c‐myc." (PMID 37243901, 2023). "Recent studies have shown that BASP1 highly expressed in cancer and promoted the proliferation of cancer." (PMID 33247706, 2020). "To further investigate the effects of BASP1 on promoting cancer metastasis, we injected luciferase-expressing Bm7-shGFP control or Bm7-shBASP1 cells intracardially into SCID mice to monitor the occurrence of metastasis by bioluminescence imaging (IVIS)." (PMID 33042262, 2020). "Accordingly, a myristoylated peptide representing the BASP1 ED interferes with the growth of v‐Myc‐transformed cells and of human cancer cell lines containing elevated MYC levels." (PMID 31944520, 2020). "BASP1 is known to localize in nucleus and harbor regulatory roles of gene transcription in cancer cells." (PMID 33042262, 2020). "Considering only normal or only cancer tissue, BASP1 expression is 1.63 ± 0.25 (P < 0.007) lower in normal tissue and not significantly different cancer tissue, in Chinese compared to US." (PMID 30917169, 2019). "For BASP1, it is 1.44 ± 0.12 fold higher in cancer compared to normal for Chinese and US tissues combined, and it is 1.85 ± 0.24 fold higher in cancer compared to normal in Chinese tissue." (PMID 30917169, 2019). "There is limited consensus in the literature regarding the role of BASP-1 in various cancers." (PMID 37894372, 2023). "Genes positively correlated with purity showed enrichment in cancer-related pathways and processes such as epithelial-mesenchymal transition (BASP1, COL4A1, THBS2), genes involved in the TNFA signaling via NFKB (SPSB1, SMAD3), and genes upregulated by KRAS activation (CFB, MAFB)." (PMID 37041233, 2023). "BASP1 was reported to be highly expressed in cancer and promotes the proliferation of cancer." (PMID 36077333, 2022). "The roles and functions of BASP1 are likely cancer type and context specific." (PMID 32923394, 2020). "It would be of interest to further investigate whether the functions of BASP1 dependent on its cellular distribution can be applied in other cancer types and which factors affect BASP1 location to have such different cell responses." (PMID 33042262, 2020). "Accordingly, the structure of the BASP1 ED could be used as template for the design of small molecules or peptides in cancer drug development." (PMID 31944520, 2020). "Accordingly, a small peptide representing the BASP1 effector domain could interfere with the proliferation of human cancer cells in which MYC is highly activated." (PMID 31058089, 2019). "Moreover, cell growth was restored in EGFR-overexpressing BASP1-knockdown cancer cells." (PMID 33042262, 2020). "mir-21 was found to be over expressed in multiple cancers down regulated tumor suppressor genes (TPM1, PTEN, PDCD4 BASP1 and RTN4) in invasion and metastasis of cancer." (PMID 21114830, 2010). "The antagonistic BASP1 effect on MYC and the MYC dependency on TNIK could enhance the development of strategies to interfere with oncogenic functions of the cancer driver MYC." (PMID 41785318, 2026). "BASP1, FAP, INHBA, and ITGA5 had been reported to be upregulated in several cancers and could regulate neuronal activity, but their relationship with DKK1, nerves, and HNSCC still remains unknown." (PMID 38525111, 2024). "Further studies are still required to explore whether BASP1 can regulate other RTKs through similar positive feedback, like EGFR, in the lipid raft for cancer progression and acquired TKI resistance." (PMID 33042262, 2020).
cancer (continued). "Hence, this result suggests that BASP1‐mediated inhibition depends on actual MYC and CaM levels in human cancer cells." (PMID 31944520, 2020). "The role of BASP1 protein in cancer has not been well established." (PMID 28212542, 2017). "Its role in the stromal compartment is not to our knowledge known, but potentially BASP1 modulation may impact a host of MYC-dependent processes in the cancer microenvironment." (PMID 26934553, 2016). "However, other predicted targets such as SOCS3, PTPRN2, MMP3, PRG1 and BASP1 have not yet been experimentally validated but could be of particular interest on cancer research." (PMID 28346474, 2017). "Although BASP1, MARCKS, and GAP43 are also expressed in non-nerve tissues, their functions in cancers are distinct." (PMID 33042262, 2020).
infection (2 papers, 2012 to 2025). The state of being infected such as from the introduction of a foreign agent such as serum, vaccine, antigenic substance or organism. "Interferes with the oncogenic capacity of MYC and its binding to calmodulinProteomics analysis of Hela cells infection with Salmonella revealed that Basp1 is one of Salmonella ubiquitin ligase SlrP on host cells." (PMID 41250600, 2025).
neurodegenerative disease (1 paper, 2020). A disorder of the central nervous system characterized by gradual and progressive loss of neural tissue and neurologic function. "By discussing GAP-43 and BASP1 in the context of neurodegenerative diseases, we also explore the therapeutic potential of modulating their activities to compensate for neuron loss in neurodegenerative diseases." (PMID 33015061, 2020). "Further exploration of these areas will facilitate the development of GAP-43- and BASP1-targeting therapies for neurodegenerative diseases." (PMID 33015061, 2020). "Interestingly, examinations of GAP-43 and BASP1 in neurodegenerative diseases reveal alterations in their expression and phosphorylation profiles." (PMID 33015061, 2020). "The involvement of disordered proteins in neurodegenerative diseases questions whether GAP-43 and BASP1 also phase separate in this context, whether this process turns aberrant, and what the functional consequences are." (PMID 33015061, 2020).